POSTN (periostin)
Diseases named in the same sentence as POSTN in open-access papers (continued):
Sharing a sentence is not in itself a finding about the gene and the disease.
tumor (continued). "POSTN, which is highly expressed by CD44+ CCA cancer cells and secreted by intrahepatic CCA stem cells (ICSCs), has a strong ability to attract tumor-associated macrophages (TAMs), in particular the M2 subtype that supports cancer aggressiveness." (PMID 36362726, 2022). "Silencing POSTN in GSCs markedly reduced TAMs infiltration, inhibited tumor growth, and prolonged survival of mice bearing GSC-derived xenografts." (PMID 35600367, 2022). "Previous studies showed that ECM molecules such as periostin and dermatopontin were important in tumor initiation and progression." (PMID 35596183, 2022). "We here extend these findings and show that POSTN can also affect primary non-tumor intestinal epithelial cells." (PMID 34795242, 2021). "Knockdown of POSTN expression decreased the abilities of HCC cell lines to form tumours in xenograft mouse models." (PMID 34193219, 2021). "Periostin is a multimodular protein secreted into the tumor microenvironment (TME), known to be overexpressed in BC." (PMID 34439139, 2021). "We previously reported the importance of full-length POSTN (PN1) in a 4T1 mouse TNBC model, and we showed that PN1 inhibition by a polyclonal antibody against exon 17 of the rat POSTN C-terminus decreased primary tumor size and inhibited lung metastasis." (PMID 33919736, 2021). "The tumor-derived astrocytes lead GBM cells to upregulate periostin and serglycin, which mediate the recruitment of M2 tumor-associated macrophages and mast cells, thereby enhancing its progression." (PMID 33804873, 2021). "PNDA-3 exhibits high affinity for periostin with a Kd of 1.07 nM and inhibits tumor growth in vivo but less effectively in vitro." (PMID 34439139, 2021). "Periostin promotes tumor cell growth through increased survival and expression in xenografted ccRCC cells promotes tumor size." (PMID 34884982, 2021). "They proposed that highly metastatic cancer cells mobilized periostin expressing CAFs in the tumor microenvironment." (PMID 34336660, 2021). "These sprouting neovasculatures not only promote the exit of dormant cancer cells but also accelerate tumor growth by secreting TGFβ1 and periostin, which are tumor-promoting factors." (PMID 34208521, 2021). "This study concluded that high POSTN levels in the tumour microenvironment resulting from the POSTN/TGFβ1 positive feedback loop can activate AP-2α to transcriptionally induce the expression of CD133, which promotes the stemness transformation of HCC cells." (PMID 34193219, 2021). "Periostin promoted the proliferation, metastasis, invasion, and clonality of PCCs, as well as tumor growth, in subcutaneous xenografts." (PMID 33824474, 2021). "ccRCC cells induced CAF-derived periostin expression, and elevated periostin promoted tumor cell itself and CAF proliferation, in return." (PMID 33777960, 2021). "After adjusting the analysis by tumor purity, we found that the expression levels of COL1A2, COL1A1, COL3A1, ZNF469 and Periostin (POSTN) were significantly correlated with tumor purity in ESCA." (PMID 33543230, 2021). "Periostin has been reported to promote tumor cell proliferation, invasion, and migration; however, we report its novel function in mediating lymphatic barrier breakdown through VE‐cadherin disruption." (PMID 33124726, 2021). "The expression levels of periostin and tenascin C were analyzed by IF of sections from si-hVDAC1-2A-TTs and si-NT-TTs to evaluate protein levels in the tumor." (PMID 34200480, 2021). "Approximately one-fourth of the H&E(–) LNs had POSTN mRNA levels in the range of those in H&E(+) LNs, suggesting that these LNs were affected by tumor cells, which in turn suggests that the LNs with low CEACAM5 levels indeed harbor tumor cells." (PMID 34192710, 2021). "Recent studies have shown that the POSTN protein plays a vital role in the formation and maintenance of the stemness-enhancing microenvironment of tumours, thus promoting tumour metastasis and invasion." (PMID 34193219, 2021).
tumor (continued). "Periostin expression in pairs of IPFfs and fibroblasts obtained from tumor tissues (IPF-CAFs) from the IPF patients (n = 6) was examined by RT-PCR." (PMID 34702952, 2021). "Here, we describe a CAF subpopulation with elevated periostin expression (periostin+CAFs), located in the primary tumor sites and metastatic lymph nodes, that positively correlated with LNM and poor survival in CSCC patients." (PMID 33124726, 2021). "The role of periostin in angiogenesis was also reported in several periostin-expressing tumor cells." (PMID 33807264, 2021). "In this study, we identified that periostin was highly expressed in IPF-activated fibroblasts apart from tumor lesions in LC-IPF." (PMID 34702952, 2021). "This suppressive cue was lost in sprouting neo-vasculature, which are characterized by reduced thrombospondin-1 expression and enhanced expression of pro-tumour factors periostin and TGF-β1." (PMID 35006432, 2021). "Due to their importance and multi-functions with respect to the ECM, we further analyzed the effect of tumor treatment with si-hVDAC1-2A on the expression of periostin and tenascin C." (PMID 34200480, 2021). "The POSTN levels in the tumour microenvironment are significantly increased in various tumours, and POSTN plays an important role in the stemness maintenance of stem cells." (PMID 34193219, 2021). "This antibody reduced periostin-secreting TNBC in a mouse xenograft model, accompanied by a decrease in the number of M2 tumor-associated macrophages and tumor vessels." (PMID 34680221, 2021). "Consistently, FAP, CD29, and periostin are up-regulated in tumor compared with normal liver tissues (n = 196 for normal liver tissue; n = 405 for tumor tissue, including 369 HCC and 36 CCA)." (PMID 32932015, 2021). "Glioma-associated microglia/macrophages (GAMs) mostly exhibit pro-tumor effects, as GSCs promote the M2 differentiation of GAMs through periostin secretion, which increases tumor growth via αvβ3 integrin." (PMID 33799798, 2021). "Multiple studies using IHC conveys, POSTN to be upregulated at the invasive front in both tumour epithelia and the surrounding matricellular space." (PMID 33739025, 2021). "Results of RT-PCR analysis of xenograft tumors showed that periostin expression was also higher in tumor cells with DIPF than in those with NHLF in both LC cell lines." (PMID 34702952, 2021). "Apart from abnormal collagen secretion, the tumour ECM contains tenascin or periostin, is more stiff and contractile, has altered organisation, and is also able to downregulate the expression of the tumour suppressor PTEN in cancer cells." (PMID 34829672, 2021). "Next, we demonstrated that higher POSTN expression promoted angiogenesis in vivo in an RCC xenograft tumor via activating IKL /AKT/mTOR pathway." (PMID 34093819, 2021). "These were mostly interstitial ECM proteins such as fibronectin, fibrinogen and periostin for PDX tumours, whereas most murine proteins in organoids were basement membrane constituents of Matrigel." (PMID 34561461, 2021). "In order to confirm the effect of POSTN in xenograft tumor growth, overexpressed POSTN were also implanted in BALB/c nude mice." (PMID 34093819, 2021). "The results proved that inhibiting the activity of the POSTN/αvβ3 pathway in HCC cells with high POSTN expression can effectively inhibit tumour growth, and the combined use of cilengitide and lenvatinib has a higher treatment efficacy." (PMID 34193219, 2021). "Further POSTN performs as a ligand for integrin's αvβ3 and αvβ5, promoting activation of multiple pathways like PI3kinase-Akt pathway leading to increased tumour cell invasion." (PMID 33739025, 2021). "Our previous research revealed that Sulf2 can stimulate the expression and secretion of POSTN through TGFβ1 in the HCC tumour microenvironment." (PMID 34193219, 2021).
tumor (continued). "Both TNC and POSTN are members of the core matrisome, which is involved in the creation of the so-called metastatic niche of human neoplasms such as colorectal cancers, brain, and breast tumors." (PMID 34944807, 2021). "POSTN formed a positive feedback loop with TGFβ1 to induce and maintain its high expression in the tumour microenvironment." (PMID 34193219, 2021). "The expression of POSTN was noted mainly in tumour stromal cells of NSCLC and, in some cases, in tumour cells)." (PMID 32987711, 2020). "Periostin promotes the acquisition of a stemness phenotype in tumor cells when it binds to Wnt ligands." (PMID 33059744, 2020). "Current studies have also demonstrated that POSTN plays pivotal roles in establishing and remodelling various tumour microenvironments." (PMID 32987711, 2020). "POSTN expression in tumour stromal cells (i.e., CAFs) was evidenced on serial sections of tissues by the positive IHC reaction for α-smooth muscle actin (α-SMA), podoplanin (D2–40), and vimentin, which are characteristic markers of CAFs." (PMID 32987711, 2020). "By comparing to the benign samples, we detected higher expressions of periostin in all three tumor types." (PMID 32719746, 2020). "The knockdown of POSTN in basal-like BC cell lines impairs mammosphere formation and tumor initiation." (PMID 33371274, 2020). "Several studies suggest that POSTN (periostin) can act to promote cell migration by facilitating the interaction between cancer cells and the tumor niche." (PMID 33613617, 2020). "Further study revealed that miR-876 regulates EMT and fibrosis via POSTN, thus promoting tumor invasion and metastasis." (PMID 33083453, 2020). "Conversely, the production of TGFβ1 and periostin by tip cells of the sprouting neovasculature can promote tumor outgrowth." (PMID 33014869, 2020). "Periosteal protein (POSTN) is a multifunctional secretory protein, which can be synthesized by both tumor and stromal cells." (PMID 32391563, 2020). "Periostin is highly expressed in the tumor stroma compared with cancer cells and promotes tumor progression and metastasis in HNSCC." (PMID 32546182, 2020). "POSTN encodes for periostin, a multifunctional ECM protein that contributes to the remodeling of the tumor microenvironment during tumor progression." (PMID 32293552, 2020). "In our study, we found that the POSTN protein was mainly located in the stromal compartment of the tumour." (PMID 32987711, 2020). "PSCs potentiate changes to the extracellular matrix, such as the secretion of collagen and periostin (osteoblast-specific factor-2), while an increasingly fibrotic stroma reduces the ability of chemotherapeutics to penetrate the tumor." (PMID 32552827, 2020). "In the analysis of clinical outcome, patients with higher periostin expression in the tumor stroma (score 2&3, n = 47) had shorter overall survival than patients with weak expression (score 1, n = 61)." (PMID 31936272, 2020). "Periostin is also essential for metastatic colonization with infiltrating tumor cells being able to induce periostin expression in the metastatic niche." (PMID 33059744, 2020). "Furthermore, as observed in other cancers, an increased expression of POSTN was also significantly associated with clinical stage, regional lymph node (N) metastasis, and the primary tumour (T) stage, suggesting that POSTN secreted by CAFs could be a key element in the progression of NSCLC." (PMID 32987711, 2020). "Subtype A cells labeled with periostin were found in the invasive front of the primary tumor, which is important for the formation of tumor capsule and metastasis." (PMID 33213510, 2020).
tumor (continued). "The main mechanism by which CAFs promote the progression of CCA is to support the proliferation and survival of tumor cells through the expression of cytokines and growth factors, such as periostin, thrombospondin-1, SDF-1, MMP2, MMP9, and IL-1β." (PMID 32539768, 2020). "Of relevance, periostin has been reported to maintain primary tumor growth, as well as to contribute to a “fertile soil” for colonization and proliferation of cancer cells in metastatic niches." (PMID 32046329, 2020). "The joint score of FN1&POSTN expression appeared to be an independent prognostic factor in terms of OS, as well as residual tumor size, presence of angioinvasion, and necrosis." (PMID 31936272, 2020). "The collagen family (COL1A2, COL1A1, COL6A3, and COL5A1), DCN, FBLN1, and POSTN were the most abundant components of the tumor ECM." (PMID 33613617, 2020). "The increased local concentration of VEGF within the GBM TME results in upregulation of periostin and tenascin C within blood vessels trapping T cells and preventing tumor penetrance." (PMID 33178210, 2020). "Glycoproteins, such as osteopontin, periostin and tenascin C are deposited either by infiltrating tumour cells or by stromal cells at the metastatic site and are important for the colonisation of tumour cells by inducing stemness-like signalling pathways." (PMID 33037194, 2020). "TGF-β1 and POSTN have been identified as tumor-promoting factors derived from endothelial tip cells." (PMID 31817646, 2019). "The perivascular niche in particular has been suggested to influence the fate of DTC by modulation of the expression of Thrombospondin-1 (supporting dormancy) and TGF-β1 and periostin (promoting tumour growth)." (PMID 31236323, 2019). "POSTN was present both at the invasive margin and in the centre of the tumours (juxta‐tumoural stroma [<100 μm] and pan‐stroma 23), as previously reported 24, while MYH11 and PDPN were found only in the centre (juxta‐tumoural stroma and pan‐stroma)." (PMID 30575030, 2019). "Periostin has the ability to activate the PI3K/AKT signaling pathway in tumor cells by interacting with integrin molecules." (PMID 31399039, 2019). "Among the various stromal constituents, periostin has received increased attention in the context of allergic inflammation, immune tolerance, wound repair, and tumor progression." (PMID 30621220, 2019). "Primary lung fibroblasts upregulated POSTN in response to tumor-derived transforming growth factor-β3 (TGF-β3) and TGF-β2." (PMID 31817646, 2019). "In an independent Swiss TMA cohort, we also observed significantly higher abundance of POSTN (P value < 0.001 by Fisher's exact test) in tumor vs, benign tissue." (PMID 31495056, 2019). "It has been shown that POSTN expression is induced in the lung by infiltrating tumor cells and this allows them to initiate colonization." (PMID 31817646, 2019). "Gene Hsa.108 (POSTN), a matricellular protein-coding gene, has been shown to regulate key aspects of tumor biology, including proliferation, invasion, matrix remodeling, and dissemination to pre-metastatic niches in distant organs." (PMID 31150453, 2019). "Accordingly, the secondary tumor we analyzed in this paper showed high POSTN levels in high-grade fragments and low POSTN levels in the low-grade ones, which is reminiscent of our results from the TMA experiment." (PMID 31052505, 2019). "Although periostin overexpression promotes the growth or motility of many types of tumor cells, its tumor-suppressing effects have also been observed." (PMID 30621220, 2019). "Morra and co-workers showed that levels of the matrix N-glycoprotein periostin that can promote EMT are higher in ccRCC than in the papillary type which correlated with tumor grading and staging as well with poor overall survival." (PMID 30863498, 2019). "Taken together, periostin seems to play a role in drug resistance, tumor growth, and metastasis in many cancers." (PMID 31412536, 2019).
tumor (continued). "In this same tumor, miR-Let-7f overexpression suppresses VM by repression of periostin (POSTN) that can induce migration of the cells." (PMID 31993365, 2019). "The accumulated knowledge about the relationship between periostin and cancer indicate that this protein modulates tumor cell behavior in many ways." (PMID 30621220, 2019). "Periostin expression was correlated with gender, smoking, tumor size, pathological N factor (pN), pleural invasion (pl), and blood-vessel invasion (v)." (PMID 30131847, 2018). "In pancreatic ductal adenocarcinoma (PDAC), POSTN has been detected in cancer epithelial cells, pancreatic stellate cells, and tumor stroma." (PMID 29946533, 2018). "Using in vivo xenograft model of TNBC, we clearly show that inhibition of periostin, in combination with chemotherapy, led to a more durable chemotherapy response by restricting the expansion of the residual mesenchymal tumor cell population." (PMID 29507310, 2018). "Among upregulated genes that are related to EMT, we are particularly interested in periostin (POSTN) due to its consistent induction in tumor cells in response to all three types of chemotherapeutic agents using human periostin-specific primers." (PMID 29507310, 2018). "Calcipotriol plus cisplatin significantly suppressed the activated HSCs-enhanced tumor progression of heat-treated residual HCC cells via the inhibited POSTN expression and the increased apoptosis." (PMID 30400797, 2018). "Standardization of the immunohistochemistry techniques used to detect POSTN in the tumor tissues (for instance, antibodies and methods of quantification) will also be necessary to reach solid conclusions." (PMID 29946533, 2018). "Several laboratories have studied the levels of POSTN in serum and its correlation with tumor burden and prognosis." (PMID 29946533, 2018). "It is believed that periostin plays a dual role in this respect as it can also act as a suppressor of tumor progression in several types of cancer." (PMID 29774119, 2018). "In OSCC, periostin promotes tumor angiogenesis, migration, and metastases, and its overexpression has been shown to enhance invasion and anchorage-independent growth and spread." (PMID 29758011, 2018). "Higher levels of POSTN in cancer epithelial cells correlated with the presence of sarcomatoid differentiation, higher tumor stage, lymph node metastases, and poor overall survival." (PMID 29946533, 2018). "POSTN levels in serum correlated with mRNA expression levels in the tumor and also with tumor size, since serum POSTN levels undergone a significant decrease after surgery." (PMID 29946533, 2018). "Another study reported that subcutaneously injected 3LL cells produced larger tumors in periostin−/− mice than in periostin+/+ mice due to impaired tumor capsule formation." (PMID 30131847, 2018). "In other study, it was shown that high POSTN expression in tumor stroma correlated with pathological grade and with survival rate in PDAC patients." (PMID 29946533, 2018). "IHC for pERK and periostin in specimens from periostin−/− and periostin+/+ mice revealed that pERK was expressed in the periphery of the primary tumor, adjacent to the periostin-positive stroma, in the periostin+/+ mice." (PMID 30131847, 2018). "Reactive host bone at the edge of growing tumours, particularly in areas of increased vascularity and fibrosis, also stained strongly for periostin." (PMID 30202513, 2018). "The idea that tumor cells or tumor stromal cells can remotely send a protein such as POSTN to prepare the metastatic niche is really exciting." (PMID 29946533, 2018). "Several studies suggest that POSTN can act facilitating the interaction between cancer cells and the tumor niche to promote cell migration." (PMID 29946533, 2018). "The queried data revealed a higher level of POSTN in HCC tissues (n = 374) than that of adjacent non-tumor tissues (n = 50) (P = 0.053)." (PMID 30400797, 2018).